MIR412 (microRNA 412)
Synonyms: hsa-mir-412; MIRN412; mir-412
Gene: MicroRNA gene on chromosome 14 (101,065,447 to 101,065,537, forward strand). Ensembl gene ENSG00000199012.
Gene Ontology:
Biological process: miRNA-mediated post-transcriptional gene silencing
Homologues: Orthologues: chimpanzee ptr-mir-412 (100% identical), macaque mml-mir-412 (100% identical), mouse Mir412 (81% identical), rat Mir412 (81% identical), guinea pig MIR412 (80% identical).